EFHD2 (EF-hand domain family member D2)
Description:
May regulate B-cell receptor (BCR)-induced immature and primary B-cell apoptosis. Plays a role as negative regulator of the canonical NF-kappa-B-activating branch. Controls spontaneous apoptosis through the regulation of BCL2L1 abundance.
Synonyms: SWS1; MGC4342
Tractability: PROTAC: ubiquitination databases record sites on it; its protein half-life has been measured.
Gene: Protein-coding gene on chromosome 1 (15,409,849 to 15,430,339, forward strand). Ensembl gene ENSG00000142634.
Subcellular location: Membrane raft
Subcellular location (Human Protein Atlas): Cytosol
Pathways (Reactome):
Signal Transduction: RHOD GTPase cycle
Gene Ontology:
Molecular function: actin filament binding; cadherin binding; calcium ion sensor activity; calcium ion binding
Biological process: actin crosslink formation
Cellular component: lamellipodium; membrane raft
Genetic constraint (gnomAD): Loss-of-function variants: 12 observed, 16.45 expected, observed/expected ratio (o/e) 0.73, 90% interval 0.47 to 1.18. The upper end of that interval is the gene's LOEUF score, 1.18, which puts it in group 5 of 6, group 1 being the genes least tolerant of losing a copy. Missense variants: 250 observed, 294.87 expected, observed/expected ratio (o/e) 0.85, 90% interval 0.76 to 0.94. Synonymous variants: 131 observed, 117.76 expected, observed/expected ratio (o/e) 1.11, 90% interval 0.96 to 1.29.
Homologues: Orthologues: chimpanzee EFHD2 (100% identical), macaque EFHD2 (100% identical), pig EFHD2 (97% identical), mouse Efhd2 (94% identical), rat Efhd2 (93% identical), zebrafish efhd2 (74% identical), tropical clawed frog efhd2 (70% identical), guinea pig EFHD2 (60% identical), rabbit EFHD2 (57% identical), Drosophila melanogaster Swip-1 (48% identical), Caenorhabditis elegans efhd-1 (46% identical), Drosophila melanogaster CG14861 (28% identical). Paralogues in human: EFHD1 (66% identical).
Diseases named in the same sentence as EFHD2 in open-access papers:
EFHD2 is named in the same sentence as 59 diseases in open-access papers, as found by Europe PMC text mining. Sharing a sentence is not in itself a finding about the gene and the disease. The quoted sentences say what the papers report.
Alzheimer disease (7 papers, 2014 to 2024). A progressive, neurodegenerative disease characterized by loss of function and death of nerve cells in several areas of the brain leading to loss of cognitive function such as memory and language. "Previously, we identified EFhd2 as a novel protein associated with tau in the brains of JNPL3 mouse model and postmortem Alzheimer’s disease (AD) and frontotemporal lobar degeneration (FTLD) cases." (PMID 38765673, 2024). "Although, EFhd2's role in promoting cell invasion and metastasis is of great interest in cancer biology, this review focusses on the evidence that links EFhd2 to Alzheimer's disease (AD) and other neurological disorders." (PMID 27064956, 2016). "How can this be reconciled with a proposed role for EFhd2 in tauopathies, such as Alzheimer's disease ?" (PMID 25133820, 2014).
melanoma (7 papers, 2013 to 2023). A malignant, usually aggressive tumor composed of atypical, neoplastic melanocytes. "EFHD2 modulating activity on cell invasion has been described in some tumours such as melanoma, where it mediates the formation of motile protrusions in association with actin and the Rho family of GTPase, while the role of EFHD2 in brain tumours is less known." (PMID 36932446, 2023). "In this study, we identified an important role of EFHD2/Swip-1 in controlling lamellipodial protrusions and cell migration of Drosophila immune cells and B16-F1 mouse melanoma cells." (PMID 35524157, 2022). "Loss- and gain-of-function analysis confirm a critical function of EFhD2/Swip-1 in lamellipodial cell migration in fly and mouse melanoma cells." (PMID 35524157, 2022). "Recently, EFHD2 enhances cell migration velocity by activating the Rho family of small GTPases in mouse B16F10 melanoma cells, suggesting the potential role of EFHD2 in cancer metastasis." (PMID 29097801, 2017). "The study showed that EFHD2 overexpression induced pulmonary metastasis in highly invasive B16F10 melanoma cells, whereas its knockdown led to metastatic inhibition." (PMID 29097801, 2017). "To experimentally test the relevance of EFhD2/Swip-1 in lamellipodium formation and protrusion in the absence of calcium gradients, we analyzed the function of EFhD2 in the highly polarized B16-F1 mouse melanoma cells forming prominent lamellipodia when migrating on laminin on a 2D surface." (PMID 35524157, 2022).
tauopathies (6 papers, 2014 to 2024). "Our previous work revealed EFhd2’s association with pathological tau in animal models and tauopathy brains." (PMID 38765673, 2024). "Against this backdrop, we discovered the calcium-binding protein EFhd2 as a tau-associated protein in a tauopathy mouse model and AD brain." (PMID 38765673, 2024). "We previously identified EFhd2 as a tau-associated protein in a tauopathy mouse model (JNPL3) and AD brains." (PMID 31456657, 2019). "In our previous studies, EFhd2 co-immunoprecipitated with pathological tau in brain extracts from AD and other tauopathies." (PMID 38765673, 2024). "Previously, our research established the connection between EFhd2 and pathological tau in both a transgenic tau model and postmortem brain tissues of tauopathies." (PMID 38765673, 2024). "These ensuing in vivo studies will enhance our understanding of EFhd2’s role in tauopathies and its potential as a target for modulating tau-mediated neurodegeneration." (PMID 38765673, 2024). "Previously, we identified the novel protein EFhd2 as a tau-associated protein in terminally ill JNPL3 mice, a tauopathy mouse model that expresses htauP301L." (PMID 30559642, 2018). "Previously, we showed that EFhd2 protein is increased in the tauopathy mouse model JNPL3, which expresses the human P301L mutant tau protein." (PMID 27064956, 2016). "Nevertheless, further studies are required to determine EFhd2's capability to enhance protein aggregation in tauopathy and other neurodegenerative disorders." (PMID 27064956, 2016). "Hence, this study provides the basis for further in vivo experiments to explore how EFhd2 modulates the biogenesis of tau aggregates in various tauopathies." (PMID 38765673, 2024). "Further experiments are required to determine the pathological role of EFhd2 in tauopathies." (PMID 30559642, 2018). "Moreover, severe tauopathy was observed in the hippocampus of EFHD2 knockout mice." (PMID 33623715, 2021). "The effect that EFhd2 has on tau proteins and its role in tauopathy is still unknown." (PMID 31456657, 2019). "Thus, it is plausible to hypothesize that formation of EFhd2 oligomers may serve as nucleation factor for tau oligomerization and, consequently, NFTs in AD and other tauopathies." (PMID 27064956, 2016). "Hence our data will in the future contribute to more specifically testing the hypotheses that EFhd2 is involved 1) in tauopathies with regard to intracellular transport, and 2) in establishment of synaptic plasticity." (PMID 25133820, 2014).
Parkinson disease (5 papers, 2016 to 2023). A progressive degenerative disorder of the central nervous system characterized by loss of dopamine producing neurons in the substantia nigra and the presence of Lewy bodies in the substantia nigra and locus coeruleus. "In this regard, EFhd2 expression is increased in substantia nigra and was found associated with Lrrk2 in Parkinson’s disease." (PMID 31456657, 2019). "Recently, we found that Calhm2 played a critical role in Parkinson’s disease (PD) by regulating EFhd2 expression in microglia." (PMID 37637999, 2023). "Altered expression of EFhd2 has been documented in AD, Parkinson's disease, Huntington's disease, Amyotrophic Lateral Sclerosis, and schizophrenia, indicating that Efhd2 gene expression is regulated in response to neuropathological processes." (PMID 27064956, 2016).
Sepsis (4 papers, 2014 to 2024). Sepsis is defined as life-threatening organ dysfunction caused by a dysregulated host response to infection. "One module positively correlated with protection and was led by the hub gene EFHD2, which encodes swiprosin-1, a calcium-binding protein involved in the macrophage response to sepsis." (PMID 38687615, 2024). "Given that EFhd2 expression in platelets is up-regulated during sepsis and has been associated with neurodegenerative processes, it is tempting to speculate that EFhd2 may be relevant for platelet functions other than clot formation such as inflammation, immune defense or wound healing." (PMID 25243606, 2014). "A study characterizing sepsis-induced changes in the MK–platelet transcriptional axis revealed that EFhd2 mRNA was highly up-regulated in mice after induction of sepsis by the cecal ligation and puncture model." (PMID 25243606, 2014).
non-small cell lung carcinoma (3 papers, 2021 to 2022). A group of at least three distinct histological types of lung cancer, including non-small cell squamous cell carcinoma, adenocarcinoma, and large cell carcinoma. "Previous studies found that EFHD2 promote cell apoptosis in murine B cells and non-small cell lung cancer cells." (PMID 34699323, 2021).
schizophrenia (3 papers, 2012 to 2017). A major psychotic disorder characterized by abnormalities in the perception or expression of reality. "Postmortem analysis of dorsolateral prefrontal cortex and mediodorsal thalamus, two brain regions associated with the pathophysiology of schizophrenia, revealed a significant increase in EFhd2 protein level in comparison to normal control cases." (PMID 27064956, 2016). "Two independent studies demonstrated that EFhd2 is up-regulated in schizophrenia." (PMID 27064956, 2016).
breast carcinoma (2 papers, 2017 to 2020). "Based on our limited examination, we found that EFHD2 was expressed in numerous types of tumor cells with highly metastatic potential, including breast cancer, pancreatic cancer, and gastric cancer, but it is undetectable in liver tumor cells." (PMID 29097801, 2017).
colorectal cancer (2 papers, 2015 to 2024). A primary or metastatic malignant neoplasm that affects the colon or rectum. "To further elucidate the molecular mechanism of EFHD2 in the inhibition of IEC apoptosis, we used human colorectal cancer cell lines HT-29 and HCT-116." (PMID 38346956, 2024).
diabetic nephropathy (2 papers, 2021). "EFHD2 overexpression enhanced mitochondria-dependent apoptosis of glomerular podocytes while silenced EFHD2 reversed this effect in the early stage of mouse diabetic nephropathy." (PMID 34699323, 2021).
glioma (2 papers, 2021 to 2023). A benign or malignant brain and spinal cord tumor that arises from glial cells (astrocytes, oligodendrocytes, ependymal cells). "To further confirm these results, we evaluated the expression levels of SH3PXD2B, SH3PXD2A and EFHD2 mRNAs and encoded proteins in IDH-wt glioma cells (U87MG and T98G) overexpressing miR-1, miR-26a-1 and miR-487b, respectively." (PMID 36932446, 2023). "In this paper, for the first time, at least to our knowledge, we demonstrate that an impaired regulation of EFHD2 by miRNAs can sustain cell migration and invasion in a glioma context." (PMID 36932446, 2023). "Despite no report with regard to the pro-EMT effect of CALU, the other two members (Cab45 and EFHD2) from the same protein family have been described in EMT regulation, which indirectly supported the potential role of CALU in glioma EMT." (PMID 33623713, 2021). "Notably, it impacts the glioma invasive phenotype by directly targeting the invadopodia-related proteins TKS4, TKS5 and EFHD2." (PMID 36932446, 2023).
lung carcinoma (2 papers, 2017 to 2024). "In lung cancer, the correlation between EFHD2 and cancer metastasis is unclear, and whether EFHD2 is related to postsurgical recurrence of stage I NSCLC remains to be determined." (PMID 29097801, 2017). "For example, EFHD2 promotes lung cancer cell resistance to chemotherapy through the NOX4-ROS-ABCC1 signaling, and high level of EFHD2 is correlated with a worse survival in lung cancer patients received chemotherapy." (PMID 39308671, 2024). "Immunostaining revealed that EFHD2 was homogeneously expressed in cancer tissue, whereas negative signals were noted in normal tissue adjacent to lung cancer." (PMID 29097801, 2017). "To evaluate EFHD2 expression in clinical samples, we performed IHC with an anti-EFHD2 antibody on the lung cancer tissue array BC041115a (US Biomax), which contains lung normal tissue, lung squamous cell carcinoma, and adenocarcinoma." (PMID 29097801, 2017).
Anxiety (1 paper, 2018). Intense feelings of nervousness, tension, or panic often arise in response to interpersonal stresses. "Slc38a3 and Gng4 expression were altered in EFhd2 knockout mouse associated with anxiety and alcohol addiction." (PMID 29391390, 2018).
colitis (1 paper, 2024). Inflammation of the colon. "Deficiency of EFHD2 in mouse IECs causes more severe intestinal symptoms in experimental colitis in vivo." (PMID 38346956, 2024). "Together, our findings suggested that EFHD2 expression was decreased in the autoimmune inflammatory intestine and Efhd2-deficient mice were more sensitive to experimental acute colitis." (PMID 38346956, 2024). "However, after challenging with 3% DSS, Efhd2-/- mice developed more exacerbated colitis, manifested with increased loss of body weight, higher disease activity index (DAI) score and reduced length of colons, compared with similarly treated WT littermate controls." (PMID 38346956, 2024). "It is noteworthy that the EFHD2 expression is significantly decreased in IECs from UC patients and experimental colitis mice at the active stage, compared to the high abundance during the steady state or the remission stage." (PMID 38346956, 2024). "To examine the possible role of Efhd2 in myeloid cells in the regulation of colitis, we generated mice with conditional knockout of Efhd2 in myeloid cells (Efhd2f/f Lyzcre/+) by crossing Efhd2f/f mice with Lyz-Cre mice." (PMID 38346956, 2024). "However, we detected the lower expression of EFHD2 protein in UC patients or mouse colon tissues with dextran sodium sulfate (DSS)-induced experimental colitis." (PMID 38346956, 2024). "Mice deficient of Efhd2 in IECs exhibit excessive IEC death and exacerbated experimental colitis." (PMID 38346956, 2024). "Taken together, these results suggested that deficiency of Efhd2 in IECs promoted IEC apoptosis, but not necroptosis, to impair the integrity of intestinal barrier and therefore caused the more severe colitis in mice induced by DSS." (PMID 38346956, 2024).
diabetes mellitus (1 paper, 2021). A metabolic disorder characterized by abnormally high blood sugar levels due to diminished production of insulin or insulin resistance/desensitization. "The result of GSE20966 showed that EFHD2 expression in the β cells of patient with diabetes mellitus was significantly higher than that in on-diabetes mellitus." (PMID 34699323, 2021).
disc degeneration (1 paper, 2019). "Interestingly, we identified three hypermethylated genes in the advanced stage of disc degeneration (CARD14, EFHD2 and RTKN2) that are involved in the regulation of the NF-κB pathway." (PMID 31513634, 2019).
lung adenocarcinoma (1 paper, 2017). A carcinoma that arises from the lung and is characterized by the presence of malignant glandular epithelial cells. "The expression of EFHD2 was significantly correlated with postsurgical recurrence of patients with stage I lung adenocarcinoma in the Kaplan-Meier-plotter cancer database search and our retrospective cohort study (HR, 6.14; 95% CI, 2.40–15.74; P < 0.001)." (PMID 29097801, 2017). "Multivariate Cox regression analysis revealed that only pathologic stage and EFHD2 expression were independent clinical predictors of disease-free survival of patients with stage I lung adenocarcinoma (P < 0.001)." (PMID 29097801, 2017). "Our results revealed that EFHD2 was significantly correlated with postsurgical recurrence of patients with stage I lung adenocarcinoma." (PMID 29097801, 2017). "In the present study, we demonstrated that EFHD2 could serve as an independent marker to predict postsurgical recurrence of patients with stage I lung adenocarcinoma." (PMID 29097801, 2017). "The percentages of cell expressing EFHD2 in cancer stage I, II, and IIIa were 36.8%, 37.5%, and 28.6%, respectively, in lung squamous cell carcinoma and 41.2%, 68.8%, and 50.0%, respectively, in lung adenocarcinoma." (PMID 29097801, 2017). "Our confocal microscopy assay revealed that EFHD2 increased F-actin structure and the formation of lamellipodia, which is consistent with the observation that EFHD2 enhanced metastatic abilities in lung adenocarcinoma cells." (PMID 29097801, 2017). "Moreover, we performed a retrospective analysis of patients with stage I lung adenocarcinoma to determine the correlation between EFHD2 protein levels and postsurgical recurrence by IHC." (PMID 29097801, 2017). "We conclude that EFHD2 expression is associated with increased metastasis and EMT and could serve as an independent marker to predict postsurgical recurrence of patients with stage I lung adenocarcinoma." (PMID 29097801, 2017). "Given that the reduction of CAV1 was not significantly correlated with postsurgical recurrence of patients with stage I lung adenocarcinoma, CAV1 is unsuitable as a coordinated molecule to improve the predictive power of EFHD2." (PMID 29097801, 2017). "Collectively, these results suggest that EFHD2 contributes to the promotion of EMT and metastasis in lung adenocarcinoma cells." (PMID 29097801, 2017). "To determine whether EFHD2 contributes to the metastatic abilities of lung adenocarcinoma cells, we used the pcDNA vector to overexpress EFHD2 in A549 cells (low endogenous EFHD2 levels) and shRNA to knockdown EFHD2 in H1299 cells (high endogenous EFHD2 levels)." (PMID 29097801, 2017). "EFHD2 increased the formation of protrusive invadopodia structures and cell migration and invasion abilities and promoted the epithelial-to-mesenchymal transition (EMT) character of lung adenocarcinoma cells." (PMID 29097801, 2017). "It is especially noteworthy that lung adenocarcinoma without EFHD2 expression present dramatically lower recurrence (8.3%, 2/24) in comparison with EFHD2-positive lung adenocarcinoma (61.5%, 16/26)." (PMID 29097801, 2017).
lymphoma (1 paper, 2022). A malignant (clonal) proliferation of B- lymphocytes or T- lymphocytes which involves the lymph nodes, bone marrow and/or extranodal sites. "The down-regulated CAPZA1, CAPZB, EFHD2, EZR and PCMT1 proteins are involved in cell–cell adhesion; their reduced levels are compatible with the metastatic behavior of lymphoma cells." (PMID 36291816, 2022).
medulloblastoma (1 paper, 2019). A malignant, invasive embryonal neoplasm arising from the cerebellum. "In the GDS4471 data set, LLM found an overexpression of the Efhd2 gene that, combined to a downregulation of Loc100132891, was able to separate most samples of classic medulloblastoma (88.3%) from the other subtypes of the same tumor." (PMID 31757200, 2019).
osteosarcoma (1 paper, 2017). A usually aggressive malignant bone-forming mesenchymal neoplasm, predominantly affecting adolescents and young adults. "The results showed that CNOT1, ASNS, and EFHD2 were overexpressed in osteosarcoma tissues compared with normal tissues, suggesting that they might play an important role in the tumorigenesis of osteosarcoma." (PMID 28188704, 2017).
rheumatoid arthritis (1 paper, 2011). A chronic, systemic autoimmune disorder characterized by inflammation in the synovial membranes and articular surfaces. "In fact, PBMC of rheumatoid arthritis (RA) patients express less EFhd2 protein than PBMC of healthy patients." (PMID 21244694, 2011).
thrombosis (1 paper, 2014). "To examine whether EFhd2-deficiency affected thrombus formation in vivo, we subjected the mice to a thrombosis model where the abdominal aorta is mechanically injured and blood flow is monitored with an ultrasonic perivascular Doppler flow probe." (PMID 25243606, 2014).